IFNA6 (interferon alpha 6)
Description:
Produced by macrophages, IFN-alpha have antiviral activities. Interferon stimulates the production of two enzymes: a protein kinase and an oligoadenylate synthetase.
Synonyms: IFN-alphaK
Tractability: Antibody: a drug acting on it is in phase 2 or 3 trials; its Gene Ontology location is reachable by antibodies, with high confidence; UniProt places it where antibodies can reach, with medium confidence; UniProt predicts a signal peptide or a membrane-spanning region.
Gene: Protein-coding gene on chromosome 9 (21,350,253 to 21,350,956, reverse strand). Ensembl gene ENSG00000120235.
Subcellular location: Secreted
Pathways (Reactome):
Immune System: Interferon alpha/beta signaling; Regulation of IFNA/IFNB signaling; TRAF6 mediated IRF7 activation
Disease: Evasion by RSV of host interferon responses; SARS-CoV-2 activates/modulates innate and adaptive immune responses
Hemostasis: Factors involved in megakaryocyte development and platelet production
Gene Ontology:
Molecular function: protein binding; cytokine activity; type I interferon receptor binding; cytokine receptor binding
Biological process: adaptive immune response; B cell activation involved in immune response; cellular response to virus; humoral immune response; natural killer cell activation involved in immune response; response to exogenous dsRNA; T cell activation involved in immune response; type I interferon-mediated signaling pathway; defense response
Cellular component: extracellular region
Genetic constraint (gnomAD): Loss-of-function variants: 0 observed, 0.0767 expected, observed/expected ratio (o/e) 0, 90% interval 0 to 1.89. That is too few expected variants to judge how well the gene tolerates losing a copy. Missense variants: 235 observed, 221.63 expected, observed/expected ratio (o/e) 1.06, 90% interval 0.95 to 1.18. Synonymous variants: 96 observed, 82.31 expected, observed/expected ratio (o/e) 1.17, 90% interval 0.99 to 1.38.
Homologues: Orthologues: chimpanzee IFNA6 (99% identical), macaque IFNA6 (96% identical), pig IFN-ALPHA-9 (69% identical), pig IFN-ALPHA-15 (69% identical), pig IFN-ALPHA-8 (69% identical), pig IFN-ALPHA-13 (68% identical), pig IFNA1 (68% identical), pig IFN-ALPHA-4 (66% identical), pig IFN-ALPHA-17 (66% identical), pig IFN-ALPHA-1 (65% identical), pig IFN-ALPHA-10 (65% identical), rabbit IF1AD2 (65% identical), and 32 more. Paralogues in human: IFNA5 (86% identical), IFNA2 (86% identical), IFNA13 (85% identical), IFNA1 (85% identical), IFNA14 (83% identical), IFNA21 (81% identical), IFNA4 (81% identical), IFNA10 (81% identical), IFNA8 (81% identical), IFNA16 (80% identical), IFNA17 (80% identical), IFNA7 (78% identical), and 4 more.
Diseases named in the same sentence as IFNA6 in open-access papers:
IFNA6 is named in the same sentence as 10 diseases in open-access papers, as found by Europe PMC text mining. Sharing a sentence is not in itself a finding about the gene and the disease. The quoted sentences say what the papers report.
COVID-19 (5 papers, 2021 to 2023). A disease caused by infection with severe acute respiratory syndrome coronavirus 2. "In contrast, IFNB1 and IFNA6 were significantly correlated with the neutrophil/lymphocyte ratio (N/L ratio), a marker of severe COVID-19 pathology." (PMID 35217532, 2022). "Both IFNA2 and IFNA6 are significantly up-regulated in the COVID-19+ cohort." (PMID 35217532, 2022). "Importantly, both MOV10 and IFNA6 have been reported in patients infected with COVID-19." (PMID 34965855, 2021). "Despite these low baseline levels, among the 7 IFNA subtypes examined we did observe some subtype differences, with notably higher levels of IFNA6 and IFNA5 in both COVID-19 patient groups and IFNA1/13 only in the hospitalized group." (PMID 36434007, 2022).
viral infection (4 papers, 2013 to 2024). "A Kruskal–Wallis test of the hDCs data revealed significant differences in log2FC between the viral infection for all genes but Ifna6 and Cfh." (PMID 39772143, 2024). "The mRNAs encoding IFNβ-dependent genes, such as IRF7, IFNα4, and IFNα6, as well as CXCL10 an established marker of viral infection, were also suppressed in DEAF1−/− MEFs." (PMID 23846693, 2013).
ZIKV infection (2 papers, 2022). "Expression analysis via qRT-PCR showed that ZIKV infection induced significant upregulation of each of the cytokines analyzed, including Ifna6, Ifnb, Ifng, Il1b, Il6, and Tnfa." (PMID 35462541, 2022).
melanoma (1 paper, 2020). A malignant, usually aggressive tumor composed of atypical, neoplastic melanocytes. "This was systematically evaluated by transplantation of B16 murine melanoma cells secreting five unique IFNα subtypes (B16_IFNα2; B16_IFNα4; B16_IFNα5; B16_IFNα6; B16_IFNα9) into a pre-clinical murine model." (PMID 32308653, 2020).
Splenomegaly (1 paper, 2011). Abnormal increased size of the spleen. "However, protection against splenomegaly was significantly improved when mice had been co-administered vectors encoding IFNα2, IFNα4, IFNα6 or IFNα9 (P < 0.05)." (PMID 21943056, 2011). "Only the co-administration of adenoviral vectors encoding IFNα2, IFNα4, IFNα6 and IFNα9 resulted in strongly improved immune protection of vaccinated mice from subsequent FV challenge infection with high control over FV-induced splenomegaly and reduced viral loads." (PMID 21943056, 2011).
tumor (2 papers, 2016 to 2020). "IFNα4, IFNα5, and IFNα6 had the remarkable capacity to delay tumor growth for well-over 100 days." (PMID 32308653, 2020). "In line with this, we found in the TCGA dataset that loss of expression of IFNA13, IFNA21, IFNA6, IFNA8, IFNB1, or IFNW1 was correlated to poor survival, increasing the evidence for the importance of the tumor-stroma microenvironment interaction in gliomagenesis." (PMID 27172220, 2016).
IFNA6 also shares sentences with these, for which no sentence is quoted: infection (3 papers); HIV-1 infection (2); lupus nephritis (1); scoliosis (1).